PARP1 (poly(ADP-ribose) polymerase 1)
Diseases named in the same sentence as PARP1 in open-access papers (continued):
Sharing a sentence is not in itself a finding about the gene and the disease.
ovarian carcinoma (continued). "This study also demonstrates that BT induces apoptosis in ovarian cancer cells via activation of proteolytic effector caspases such as Caspase 3 and 7 and subsequent cleavage/inactivation of PARP-1 (involved in DNA repair)." (PMID 24495391, 2014). "Real-time PCR and immunohistochemical analysis showed that PARP1 mRNA and protein were overexpressed in ovarian cancer tissues, compared to normal ovarian tissues (P < 0.05; each group n = 10)." (PMID 23442605, 2013). "Poly (ADP-ribose) polymerase 1 (PARP1) overexpression plays a critical role in ovarian cancer progression and the clinical development of PARP1 inhibitors to treat BRCA-mutated ovarian cancer has advanced rapidly." (PMID 23442605, 2013). "We therefore investigated the methylation status of the PARP1 promoter region and its correlation with PARP1 expression in BRCA-mutated ovarian cancer." (PMID 23442605, 2013). "Serous ovarian cancer tissues displayed decreased DNA methylation in the promoter region of PARP1 compared to normal tissue, and methylation intensity correlated inversely with PARP1 mRNA levels." (PMID 23442605, 2013). "A series of new therapeutic agents that are potent inhibitors of the PARP1 and PARP2 isoforms have demonstrated important clinical activity in patients with breast or ovarian cancers that are caused by mutations in either the BRCA1 or 2 genes." (PMID 22401667, 2012). "The most advanced case is the PARP-1 inhibitors, on their own or in combination with DNA-damaging chemotherapeutics, which are in phase-II clinical trials with breast/ovarian cancer patients having BRCA1/BRCA2 null tumours." (PMID 19319136, 2009). "Apparently, the onset of caspase activation and PARP-1 inactivation in SKOV-3 ovarian cancer cells by Fe-SP resulted in the morphological hallmarks of apoptosis observed." (PMID 18509533, 2008). "Indeed, EVs carrying CRISPR/Cas9-encoding plasmids targeting the poly (ADP-ribose) polymerase-1 (PARP-1) gene were shown to block PARP-1 in ovarian cancer cells, demonstrating preserved transcriptional activity of the recombinant DNA cargo during delivery." (PMID 40430932, 2025). "Interestingly, the authors described high uptake of [18F]PARP1‐inhibitor in five low‐grade ovarian cancer lesions." (PMID 40923371, 2025). "Moreover, the interaction between APEX1 and KAT6A or PARP1 was enhanced in PARPi‐resistant ovarian cancer cells during olaparib + cisplatin treatment, indicating the formation of a more stable complex containing KAT6A, PARP1, and APEX1." (PMID 38973255, 2024). "Veliparib was first studied in ovarian cancer and targets PARP1 and PARP2 enzymes." (PMID 39334297, 2024). "Notably, our analysis of these clinical samples revealed more interactions between KAT6A and PARP1 in PARPi‐resistant ovarian tumors than in primary ovarian cancer, suggesting a potential role of KAT6A in PARPi resistance." (PMID 38973255, 2024). "Additionally, the interaction between KAT6A and PARP1 was enhanced in PARPi‐resistant ovarian cancer cells treated with olaparib and cisplatin in vitro." (PMID 38973255, 2024). "But PARP-1 is overexpressed and may also stimulate angiogenesis in epithelial ovarian cancer cells by increasing the expression of VEGFA." (PMID 39624625, 2024). "Notably, synthetic lethality was demonstrated with BRCA1/2 alterations in ovarian cancer and inhibition of poly (ADP-ribose) polymerase 1 (PARP1)." (PMID 38473300, 2024). "It has been shown that siRNA-mediated PARP1 or a drug that inhibits PARP1 could lead to increased STAT3 phosphorylation in ovarian cancer cell lines." (PMID 37588193, 2024). "Several methods for determining PARP-1 levels in biological material have been developed, including the quartz crystal microbalance (QCM), which showed PARP-1 levels to be low in normal ovarian cells (6.78 ng∙mL−1) and elevated in the presence of ovarian cancer (84.75 ng∙mL−1)." (PMID 36831138, 2023).
ovarian carcinoma (continued). "In addition, the downregulation of let-7e enhances DNA repair by targeting PARP1 and thus induces cisplatin resistance in ovarian cancer." (PMID 37583428, 2023). "However, some PARPi-resistant ovarian cancer cell lines with relatively high PARP-1 expression levels have low PAR levels, indicating that the cellular genetic background influences PARP-1 activity and PAR turnover." (PMID 37609662, 2023). "In our studies, the MEnZnCuo could synergy with the PARP1 inhibitor to inhibited the ovarian cancer lines." (PMID 37206208, 2023). "As PARP1 inhibition can increase Fra-1 expression without affecting c-Jun expression, AP-1 (Fra-1/c-Jun) inhibition combined with PARP1 inhibition therapy may serve as a new joint therapy for breast and ovarian cancer patients." (PMID 37483616, 2023). "Because MCF7 MAGI1 KO cells showed defects in their DNA repair machinery, we tested whether olaparib, a PARP1 inhibitor used in patients to treat certain subtypes of breast and ovarian cancers, would render MCF7 MAGI1 KO cells more sensitive to cisplatin." (PMID 37566008, 2023). "PARP1 inhibitor has been applied in the clinic to treat BRCA1/2 mutated breast and ovarian cancer." (PMID 37483616, 2023). "Recent studies showed that results of the treatment with PARP1 inhibitors in breast and ovarian cancers may be dependent on high expression, particularly for miRNAs, and low expression of BRCA1." (PMID 36831687, 2023). "Finally, alternative and novel PARP1 inhibitors, including olaparib, rucaparib, veliparib and talazoparib, are currently being developed or used for the treatment of (ovarian) cancer." (PMID 35163765, 2022). "In ovarian cancer, several studies suggested that high expression of PARP1 may be a potential marker for predicting poor prognosis and platinum resistance of the patients." (PMID 35875162, 2022). "The PARP-1 inhibitors can selectively kill the cancer cells with homologous recombination (HR) defect caused by BRCA1/2 mutations, and have been approved for the therapy of cancers such as ovarian cancer, prostate cancer and breast cancer, etc." (PMID 36353483, 2022). "Based on in vitro study results, PARP1 protein level in ovarian cancer cells might be a potential marker to predict the combo effect of PARPi and AKTi." (PMID 35419627, 2022). "As of 2021, US Food and Drug Administration (FDA) and European Medicine Agency (EMA) have approved four PARP-1 inhibitors as anti-cancer therapies for breast or ovarian cancer, namely: Olaparib (IC50 = 13 nM), Rucaparib (IC50 = 80 nM), Niraparib (IC50 = 35 nM), and Talazoparib (IC50 = 3 nM)." (PMID 35158955, 2022). "In another study, cancer cell-derived EVs were employed to efficaciously distribute CRISPR/Cas9 plasmids for the targeted suppression of poly (ADP-ribose) polymerase-1 (PARP-1), which promotes cell death (apoptosis) in ovarian cancer cells, improving their cisplatin sensitivity." (PMID 35159299, 2022). "As previously reported, PARP1 expression level could drive anti-tumor activity of combination treatment with PARP inhibitor, PARP1 protein level was further studied in these ovarian cancer cell lines." (PMID 35419627, 2022). "It has been demonstrated that CRISPR-induced inhibition of PARP1 synergizes cisplatin cytotoxicity in ovarian cancer, which may lead to a potential concurrent platinum and PARP inhibition, instead of using small molecule inhibitors." (PMID 35205694, 2022). "Besides being a form of therapeutics to fight breast and ovarian cancer in DSBR-deficient patients, PARP1 inhibitors are also used in cardiac diseases and infection to suppress overexpressed PARP1." (PMID 33482196, 2021). "Consequently,In vivo studies on taxifolin induced in apoptosis of HCT116 and HT 29 cells revealed PARP1 overexpression is responsible for ovarian cancer." (PMID 34727985, 2021). "LncRNA NEAT1 regulates miR-770-5p/PARP1 signaling to induce cisplatin resistance in ovarian cancer." (PMID 34660304, 2021).
ovarian carcinoma (continued). "One of the new treatment options could be the application of poly (ADP-ribose) polymerase 1 (PARP1) inhibitors, which are already used in breast and ovarian cancer therapy." (PMID 33572647, 2021). "The poly(adenosine diphosphate ribose) polymerase (PARP) family of DNA end-binding core proteins is involved in one such DNA repair pathway, and inhibition of PARP1 (PARPi) has emerged as a promising therapeutic approach for the treatment of certain cancers, particularly breast and ovarian cancers." (PMID 33801877, 2021). "In order to repair the generated genotoxicity and DNA damage induced by the lactam steroidal alkylators ASA-A and ASA-B, the cells of all the examined human ovarian cancer cell lines responded with significantly elevated transcription levels of PARP1 and PARP2 mRNA." (PMID 34440232, 2021). "Thus, an increased level of PARP-1 expression was observed in lung, prostate, uterus, and ovarian cancers." (PMID 33572586, 2021). "PARP1 have been shown to involved in cisplatin resistance in ovarian cancer, and could be treated as a potential sensitizer in cisplatin chemotherapy." (PMID 34858477, 2021). "This demonstrates that PARP-1 may serve as a suitable drug target for Auger therapy in breast and ovarian cancer patients that have high PARP-1 expressing tumors." (PMID 33352773, 2020). "Therefore, PARP1 is reportedly overexpressed in multiple cancers including those involving BRCA1/2 mutation, neuroblastoma, ovarian cancer, human papilloma virus-infected oropharyngeal carcinoma, Ewing’s sarcoma, and colon cancer." (PMID 33324554, 2020). "PARP1 mediated ADP ribosylation is a critical step in single-strand D.N.A. damage repair, and its inhibition is synthetically lethal in BRCA1 deficient breast and ovarian cancers." (PMID 32455851, 2020). "Furthermore, 1132 breast (grey dotted box) and 420 ovarian cancer (black dotted box) patients’ tumors had significantly higher expression of PARP-1 in both cancers compared to all normal tissues except bone marrow and spleen (one-way ANOVA; p-value < 0.05)." (PMID 33352773, 2020). "Taking advantage of the tropism towards their cell of origin, exosomes produced from SKOV3 ovarian cancer cells, designed to contain Cas9 protein and sgRNA specific for poly (ADP-ribose) polymerase-1 (PARP‐1), were introduced by electroporation to knock out PARP‐1." (PMID 33353099, 2020). "PARP1 is shown to impact invasion of ovarian cancer cells stimulated by HGF." (PMID 33133138, 2020). "In recent years, PARP1 inhibitors have extensively been explored as anticancer drugs either as single agent or in combination with other conventional chemotherapeutic drugs for treatment of breast and ovarian cancers." (PMID 31856867, 2019). "The possibility of personalising the treatment according to the mutational state, as occurs in the choice of treatments with platinum compounds and poly (ADP-ribose) polymerase 1 (PARP1) inhibitors in patients with ovarian cancer, has extended the recommendation to most international guidelines." (PMID 31545835, 2019). "Treatment of ovarian cancer cells with cisplatin may elevate poly [ADP-ribose] polymerase 1 (PARP-1), which is important for cell survival by regulating autophagy." (PMID 31245292, 2019). "Olaparib (AZD2281) is an oral PARP-1 and -2 inhibitor largely tested among ovarian cancer patients." (PMID 30820349, 2019). "Notably, the translational potential of PARP-1 PET imaging agent to test PARP1 expression has been examined in a preclinical model of ovarian cancer." (PMID 31242618, 2019). "Furthermore, we used Olaparib, the PARP1 targeting drug used for ovarian cancer, and compared the response of cells to Mortaparib and Olaparib." (PMID 31856867, 2019).
ovarian carcinoma (continued). "Olaparib, rucaparib, niraparib, and talazoparib targeting PARP1/2 have been approved by the United States Food and Drug Administration (FDA) for the treatment of breast or ovarian cancer in patients harboring HR mutations that induce synthetic lethality in the BRCA1 or BRCA2 gene." (PMID 31795418, 2019). "Furthermore, PARP1 inhibitors act synergistically with chemotherapy in SNP carrier cells (especially in ovarian cancer for which olaparib is FDA-approved), but they are additive at best in wild-type cancer cells." (PMID 30824778, 2019). "To determine whether PARP1 overexpression contributes to the survival and/or proliferation of ovarian cancer cells, we applied PJ-34 to cultured cancer cells, A2780, HEY and HO8910, and evaluated apoptosis and cell cycle progression." (PMID 29684820, 2018). "In this report we studied the role of PARP1 in the proliferation of ovarian cancer cells." (PMID 29684820, 2018). "Low or no expression of BRCA1 in breast and ovarian cancers is associated with a good clinical response to treatment with platinum therapies and PARP1 inhibitors." (PMID 29021870, 2017). "Therefore, we strongly believe that ctDNA can give new insights into pathogenesis of ovarian cancer and response of the patients to PARP1 inhibitors." (PMID 29254167, 2017). "Rucaparib was the first PARP-1 inhibitor to enter clinical trials and olaparib was the first PARP-1 inhibitor to gain FDA approval for the treatment of germline BRCA-deficient ovarian cancer." (PMID 27515310, 2016). "In addition, we found that combined inhibition of BRCA2 and PARP1 in vivo delayed the growth of ovarian cancer tumors." (PMID 26959114, 2016). "Poly (ADP-ribose) polymerase 1 (PARP1) plays a critical role in ovarian cancer progression." (PMID 24448423, 2014). "Our findings imply that the genetic (such as BRCA1 mutation) and epigenetic mechanisms (such as hypomethylated ETS1 motif, and histone modification H3K9ac and transcription factor ETS1 binding) are jointly involved in the malignant progression of PARP1-related ovarian cancer." (PMID 24448423, 2014). "The recent success of PARP1 inhibitors (that block BER and SSBR) in germ-line BRCA deficient ovarian cancer provides evidence that targeting DNA repair is an important area for personalization of ovarian cancer therapy." (PMID 26674120, 2014). "Beyond prostate cancer and Ewing sarcoma, PARP-1 inhibitors could be used to selectively kill Ets-1-expressing tumours in numerous cancers such as breast, lung, colorectal or ovarian carcinomas." (PMID 23405229, 2013). "If we can clarify the mechanism behind high PARP1 expression from an epigenetic point of view, a more specific epigenetic therapy could be developed for ovarian cancer." (PMID 23442605, 2013). "Recent findings have shown the curative effect of PARPi treatment in cancer depends mainly on its capacity to trap PARP1 on chromatin; thus, platinum‐sensitive ovarian cancer patients without HR‐deficient tumors could also benefit from PARPi treatment." (PMID 38973255, 2024). "Though the mechanism has yet to be explored, studies have shown that platinum-treatment-resistant epithelial ovarian cancer (EOC) tissue has even greater levels of PARP1 expression, leading to speculation of its potential as a marker for predicting poor prognosis and platinum resistance." (PMID 39272943, 2024). "Kim and collaborators have reported that cancer-derived exosomes loaded CRISPR/Cas9 could restrain the expression of poly(ADP-ribose) polymerase-1 (PARP-1) to enhance the chemosensitivity of cisplatin and achieve satisfactory therapeutic effects in ovarian cancer tumors." (PMID 38926780, 2024). "The lncRNA GAS5 may regulate the expression of PARP1 by recruiting the transcription factor E2F4 to its promoter, affecting the activity of the MAPK signalling pathway, promoting apoptosis and causing G0/G1 arrest in ovarian cancer cells." (PMID 35725373, 2022).
ovarian carcinoma (continued). "In addition, HMGB3 facilitated the development of PARPi resistance by directly interacting with PARP1 in ovarian cancer cells, and the inhibition of HMGB3 combined with PARPi might have broad prospects in the clinical therapy of ovarian cancer." (PMID 35332131, 2022). "The genotyping results indicated that the PARP1 rs8679 and hOGG1 rs293795 A>G polymorphisms were associated with the decreased ovarian cancer risk under a dominant model, while LIG3 rs4796030 A>C polymorphism with an increased ovarian cancer risk under a recessive model." (PMID 33391423, 2021). "Therefore, PARP-1 inhibitors (PARPi), either as single agent or in combination with other chemotherapeutic agents, are being extensively explored in tumors bearing defects in homologous recombination (HR) pathways such as breast and ovarian cancer." (PMID 31303961, 2019). "Rucaparib is a potent PARP-1 and PARP-2 oral inhibitor, which is approved by FDA in December 2016 and by EMA in May 2018 as monotherapy for the treatment of advanced BRCA-mutated ovarian cancer, relapsed after at least two chemotherapy lines." (PMID 31109041, 2019). "In addition to the upregulation of NRF2 antioxidant function, repression of NADPH oxidases, an important source of ROS, by PARP1 may also contribute to the maintenance of redox homeostasis in ovarian cancer cells." (PMID 29684820, 2018). "Finally, Rucaparib is another PARP1/2 inhibitor undergoing clinical studies in ovarian cancer." (PMID 28008141, 2017). "PARP1, a molecular sensor of DNA damage, is activated when DNA is damaged and is thought to play a role in a variety of diseases, such as diabetes, arthritis, Parkinson’s and Alzheimer’s diseases, cerebral ischemia, traumatic brain injury, and some malignancies such as ovarian carcinoma." (PMID 26526840, 2016). "Niraparib is also an oral inhibitor of PARP-1 and PARP-2, which has gained promising results of maintenance therapy in ovarian cancer." (PMID 40821840, 2025). "Specially, a study reported that the combination of EZH2 inhibitors and PARP1 inhibitors enhanced lethality in homologous recombination (HR)-proficient and CARM1-high ovarian cancer." (PMID 40661778, 2025). "PARP1 disrupted the interaction of FOXQ1 and CHIP in ovarian cancer cells, which increased the protein levels of FOXQ1." (PMID 39777582, 2025). "Given that Ets‐1 is known to be overexpressed in ovarian cancer and has been suggested as a poor prognostic factor, it seems reasonable to speculate that the oxidative stress‐mediated antitumor effect, observed after PARP‐1 inhibition, is the result of the transcriptional activity of Ets‐1." (PMID 39778077, 2025). "Exosomes carrying CRISPR/Cas9 have been shown to suppress poly (ADP-ribose) polymerase-1 (PARP-1) expression, inducing apoptosis in ovarian cancer cells." (PMID 40757000, 2025). "In PARPi‐resistant ovarian cancer cells, the liquid–liquid phase separation (LLPS) of KAT6A reduced the cytotoxic effects of PARPi treatment by releasing PARP1 trapped at the DNA break sites." (PMID 41357671, 2025). "The discovery of a synthetically lethal interaction between PARP1 and BRCA led to the development of PARPi, thereby demonstrating the clinical viability of this DNA-repair-directed approach for treating ovarian cancer." (PMID 39135999, 2024). "PARP-1 is a distinct biomarker found in various malignancies, including glioblastoma multiforme (GBM), breast, prostate, and ovarian cancer." (PMID 38666920, 2024). "PARP1 inhibitors and other DDR-targeting drugs have demonstrated efficacy in treating breast and ovarian cancers." (PMID 39185402, 2024). "Here, KAT6A LLPS also enhanced the subsequent DDR capacity by impairing PARP1 trapping and reducing PARP1‐DNA complexes, which attenuated the cytotoxic effects of PARP1 trapping, leading to resistance to PARP inhibitors in ovarian cancer cells." (PMID 38973255, 2024). "Another selective and potent PARP-1 inhibitor, AZD9574, revealed efficacy in breast and ovarian cancer cells." (PMID 39201718, 2024).